STAT3 (signal transducer and activator of transcription 3)
Diseases named in the same sentence as STAT3 in open-access papers (continued):
Sharing a sentence is not in itself a finding about the gene and the disease.
breast cancer (continued). "In the present study, we used Bazedoxifene (DUAVEE®; BZA), which directly binds the GP130 receptor to inhibit IL-6-induced STAT3 activation in breast cancer." (PMID 39768178, 2024). "The OA derivative CDDO-Me inhibited Janus kinase (JAK) and signal transducer and activator of transcription 3 (STAT3) pathways in MDA-MB-468 breast cancer cells." (PMID 39064870, 2024). "It has been reported that NONO can interact with STAT3 proteins to increase their stability and promote transcription of STAT3 target genes in breast cancer cells." (PMID 39695095, 2024). "It was later shown that Aiolos cooperated with STAT3 to drive chemokine receptor expression and promote breast cancer metastasis." (PMID 39560993, 2024). "Clinically, CXCL1 was shown to be an independent predictor of poor prognosis and to be positively correlated with IGF1R/STAT3/HMGB1 expression in breast cancer." (PMID 39394189, 2024). "Consistent with previous studies, the HMGA2 oncogenic pathway is shown to be enhanced by STAT3 signaling modulated Let-7a expression in breast cancer and glioblastoma cells 39-41." (PMID 39664573, 2024). "Transcriptional upregulation of MEK5 by signal transducer and activator of transcription 3 (STAT3) enhances the epithelial–mesenchymal transition in breast cancer cells, facilitating their invasion and metastasis." (PMID 38785963, 2024). "BP1003 efficiently reduces STAT3 expression and enhances the sensitivity of breast cancer cells (HER2+, triple negative) and ovarian cancer cells (late stage, invasive ovarian cancer) to paclitaxel and 5-fluorouracil (5-FU) in both 2D and 3D cell cultures." (PMID 39200368, 2024). "Western blotting results showed that the expression levels of p-JAK2 and p-STAT3 in breast cancer cells were significantly decreased after PSP treatment." (PMID 38872110, 2024). "In 2012, PTPN9 was first reported to induce STAT3 dephosphorylation, suppressing breast cancer growth." (PMID 38920657, 2024). "B6, for example, induced apoptosis in breast cancer cells by constitutively inhibiting STAT3 phosphorylation through allosteric interaction with JAK2, implying that JAK2 is essential for STAT3 activation." (PMID 38182570, 2024). "Conversely, vascular endothelial growth factor‐alpha (VEGF) upregulates the expression of Myc and Sox2 through its receptor VEGFR‐2, thereby enhancing the self‐renewal capacity of breast cancer stem cells via the JAK2/STAT3 pathway." (PMID 39558881, 2024). "Our findings corroborate Ahn's discovery that the ShcA pathway triggers STAT3-mediated immunosuppressive signals in breast cancer cells." (PMID 38763954, 2024). "For example, in breast cancer, the LINC00908-encoded polypeptide ASRPS (a small regulatory peptide of STAT3), the lncRNA MAGI2-AS3-encoded polypeptide, and the lncRNA HCP5-encoded peptide have been proven to have functional roles in breast cancer pathogenesis." (PMID 39346726, 2024). "Earlier in vitro research showed that co-administration of luteolin and paclitaxel in MDA-MB-231 breast cancer cells induces apoptosis through the suppression of signal transducer and activator of transcription 3 (STAT3) gene." (PMID 39176367, 2024). "Previously, it has been demonstrated that in MCF7 breast cancer cells, STAT3 collaborates with FRA1 and c-JUN AP1 components to activate the MMP9 promoter, while in HepG2 hepatoma cells, STAT3 associates with HDAC1 to inhibit IL6-induced CCL2 transcription." (PMID 39274912, 2024). "Via downregulation of Akt and STAT3 pathways, CA derivate was reported to suppress the expression of P-gp in triple-positive drug-resistant breast cancer cells." (PMID 38543147, 2024). "SH003 also induces autophagy via inhibiting STAT3 activation while sustained activation of STAT3 weakens SH003-induced autophagy in breast cancer cell." (PMID 38303001, 2024). "The hypoxic bone marrow environment reduces the LIFR/STAT3/SOCS3 signaling pathway in breast cancer cells." (PMID 39494330, 2024).
breast cancer (continued). "On the one hand, an online database (NRF2-ome) predicted the potential interplay of NRF2 with STAT3 based on domain-motif interactions; which was confirmed in human breast cancer cells." (PMID 38755517, 2024). "Intriguingly, garcinol was also found to impede NF-κB/STAT-3 signaling cascade in vitro and also substantially reduce breast cancer growth in NOD-SCID mice." (PMID 38435669, 2024). "In ER positive breast cancer cells, these alterations favor STAT3-dependant transcriptional activation of the S100A7 gene." (PMID 39830522, 2024). "Although the sample size is limited, these clinical sample results further corroborate our findings on STAT3-mediated SUSD2 upregulation in EGFR+ HER2+ breast cancer, underscoring the clinical significance of SUSD2 expression." (PMID 39791720, 2024). "Mechanistically, exogenous FGF21 treatment enhanced the anti-apoptotic ability of breast cancer cells through STAT3 and Akt/FoXO1 signaling pathways, and mitigated doxorubicin-induced cell death." (PMID 38238320, 2024). "Stattic has also induced growth inhibition in several cancer cell lines and the human laryngeal squamous cell UM-SCC-17B xenografts and stattic induced apoptosis in STAT3-dependent MDA-MB-435S breast cancer cells." (PMID 38339245, 2024). "When cultured in vitro, MMe were able to activate signal transducer and activator of transcription 3 (STAT3) signaling, which is a pathway of interest in the development of breast cancer." (PMID 39525621, 2024). "Hallmark Il6 Jak Stat3 Signaling (Overlap Genes: INHBE, REG1A): This signaling pathway is involved in inflammation and immune responses and has been linked to breast cancer progression and metastasis." (PMID 39000413, 2024). "STAP-2 also binds to breast tumor kinase (BRK) and STAT3, resulting in the enhanced growth of T47D breast cancer cells." (PMID 38745775, 2024). "Recent literature indicates that PRMT6 promotes breast cancer migration and distant metastasis by methylating STAT3, thereby regulating the IL-6/STAT3 pathway." (PMID 38637831, 2024). "In breast cancer, HER2 overexpression has been linked to STAT3 expression and a HER2-STAT3 signaling network." (PMID 38601214, 2024). "Our study demonstrates, for the first time, that co-targeting tGLI1 and IL-6R/GP130/STAT3 signaling pathways is synergistic against HER2-enriched breast cancer and TNBC, warranting future clinical investigations." (PMID 39768178, 2024). "IL-6, stimulated through STAT3, fosters malignant properties, expanding the breast cancer stem cell population." (PMID 38347830, 2024). "IL-17 directly enhances the proliferation of keratinocytes, promotes MMP-dependent cell invasion, supports angiogenesis, inhibits TGF-β-dependent apoptosis, and enhances MEK-, ERK-, JNK-, and STAT3-mediated breast cancer cell proliferation." (PMID 39205642, 2024). "Similar results were found in breast cancer; EGFR/STAT3 has been recognized as a critical signal axis for primaquine-mediated c-Myc down-regulation to induce apoptosis in breast cancer cells." (PMID 39338323, 2024). "FLLL32was a represented STAT3 inhibitor that suppressed the tumor growthof breast cancer, PDAC in vitro and in vivo." (PMID 38559310, 2024). "For example, TAMs promote the CSC-like phenotypes in breast cancer via activating a paracrine EGFR/STAT3/SOX-2 signaling pathway." (PMID 38245798, 2024). "Amongst the top significant terms from Elsevier pathways, proteins involved in altered expression in cancer metastases, breast cancer related terms, and specifically, STAT3 and NFKB mediated activation of inflammation induced tumorigenesis were listed." (PMID 39281650, 2024). "Decreased PD-L1 levels were noted in MDA-MB-231 breast cancer cells with constitutive STAT3 suppression using selective STAT3 inhibitors." (PMID 38339245, 2024). "Prior research has demonstrated that TM4SF1 has the ability to initiate the JAK2/STAT3 signaling pathway in breast cancer, hence facilitating the spread of breast cancer to several target organs." (PMID 38762481, 2024).
breast cancer (continued). "STAP-2/BRK expression is deregulated in breast cancers and enhances STAT3-dependent cell proliferation." (PMID 38745775, 2024). "For instance, arctigenin has been reported to inhibit proliferation and induce apoptosis in breast cancer cells in vitro by targeting the transcription factor STAT3." (PMID 39717276, 2024). "The obesity‐related protein FTO drives ADM resistance in breast cancer by activating the STAT3 pathway." (PMID 39558881, 2024). "In breast cancer, the CXCL12/CXCR4/ACKR3 axis promoted breast cancer metastasis through the activation of the STAT3 pathway." (PMID 38920657, 2024). "In breast cancer, miR‐4532 stimulated cell proliferation, anti-apoptosis, disease pathogenesis, disease relapse/metastases and activation of STAT3 and TGFB pathways." (PMID 39677943, 2024). "Downstream of EGFR s-nitrosation, oncogenic signaling pathways, including c-Myc, Akt, STAT3, and β-catenin, are activated in breast cancer." (PMID 38601214, 2024). "In summary, our study reveals a novel mechanism of OVOL2 as a tumor suppressor in breast cancer, inhibiting tumor stemness and metastasis through STAT3 signaling pathway and FAO inhibition." (PMID 38627980, 2024). "STAT3 is currently considered an oncogene, and aberrant regulation of STAT3 has been reported in many different tumors, such as glioma, thyroid cancer, breast cancer, lung cancer, osteosarcoma and so on." (PMID 39000312, 2024). "Meanwhile, breast cancer cell-derived exosomal lncRNA HAGLROS induces TAM/M2 polarization through the p-STAT3 pathway and enhances malignant evolution of breast cancer cells." (PMID 39198393, 2024). "Leptin favors human epidermal growth factor receptor 2 (HER2) protein concentration through a STAT3-mediated mechanism and the upregulation of the heat shock protein (Hsp90) in breast cancer cells." (PMID 38785834, 2024). "Another ongoing phase II randomized study (NCT05689619) is ongoing in Italy, comparing silibinin (an oral STAT3 inhibitor) with a placebo in single brain metastasis from breast cancer and NSCLC following complete resection." (PMID 38893253, 2024). "In preclinical studies, Palbociclib-resistant breast cancer cells demonstrated upregulation of the IL-6/STAT3 pathway, and treatment with TTI-101 significantly increased cell death." (PMID 38339245, 2024). "Many studies documented that STAT-3-mediated breast cancer metastasis happens through the upregulation of MMP9 and MMP2 expression." (PMID 38673967, 2024). "DiMeOC-Mg-BCD decreased the expression of metalloproteins, IL-6, and STAT3 in the MDA-MB-231 breast cancer cell line, leading to the induction of apoptosis." (PMID 38673967, 2024). "In some tumor types, such as acute leukemias and breast cancer, either STAT3, STAT5, or both can be found to be activated inappropriately." (PMID 38611065, 2024). "This G-quadruplex, known as T40214 or STAT, has demonstrated its antiproliferative effects on the STAT3 pathway in both prostate cancer and breast cancer." (PMID 39598347, 2024). "Further investigations reveal that the CXCL12/CXCR4 axis phosphorylates JAK2, thereby activating the STAT3 signaling pathway to promote breast cancer proliferation and metastasis." (PMID 38920657, 2024). "To date, two IL-6Rα monoclonal antibodies (mAbs), a JAK1/2 inhibitor, and a small-molecule STAT3 inhibitor are being clinically investigated for breast cancer." (PMID 39768178, 2024). "JAK2/STAT3 signaling pathway takes part in the development of chemoresistance in breast cancer by increasing carnitine palmitoyl transferase 1B (CPT1B) and fatty acid beta-oxidation (FAO)." (PMID 38892394, 2024). "A study of breast cancer in mice also established cross-talk between the signal transducer and activator of transcription 3 (STAT3) pathway and SOX2 expression." (PMID 39095874, 2024). "High-salt mediated NFAT5/STAT3 signaling activation in breast cancer cell aids in proliferation and migration through activation of angiogenic factor VEGF-A." (PMID 39152497, 2024).
breast cancer (continued). "Inhibition of either CXCR4 or JAK2 suppresses STAT3 phosphorylation, reversing the proliferative and metastatic phenotypes of breast cancer." (PMID 38920657, 2024). "STAT3 increases the expression of c-Myc and the metastasis regulator Twist genes and is, therefore, thought to induce breast cancer." (PMID 39057095, 2024). "We show that breast carcinoma cells and CAFs sustain a cooperative relationship through a STAT3-driven positive feedback loop that stimulates a pro-tumorigenic phenotype in breast carcinoma cells in a 3D culture system." (PMID 39199680, 2024). "The active form of phosphorylated STAT3 has been found to induce upregulated expression of cdc2, cyclin B1, m-ras, and E2F-1 in colon and breast carcinomas." (PMID 38256080, 2024). "In general, pro-tumorigenic effects were reported for STAT3 in malignancy, including in breast cancer, through the promotion of tumor cell proliferation, EMT, invasion and angiogenesis." (PMID 37190183, 2023). "They summarized a large variety of STAT3 inhibitors which reverse cisplatin resistance in lung cancer, ovarian cancer, cervical cancer, breast cancer, laryngeal cancer, head and neck cancers, esophageal cancer, and hepatocellular carcinoma." (PMID 36902166, 2023). "Several studies have revealed that TAMs induce tumor chemoresistance through various mechanisms, and mammary tumors reduce the therapeutic response to anti-cancer drugs through mechanisms, such as IL-10/STAT3/Bcl2 signaling." (PMID 37369757, 2023). "Our previous study revealed that the overexpression of NDRG2 suppressed the migration and invasion of breast cancer cells by repressing the STAT3/Snail signaling pathway, which plays an important role in cell survival, mortality, and proliferation." (PMID 37958443, 2023). "In contrast, whole-genome sequencing analysis of 170 breast cancer patients demonstrated that distant metastasis from ER-positive patients causes JAK2 and STAT3 mutations, producing late inactivation of the formerly active cascade." (PMID 37834225, 2023). "In breast cancer, curcumin can increase M1 and decrease M2 macrophages, resulting in a decrease in STAT3, IL-10, and arginase I gene expression and secretion in mice with metastatic breast cancer." (PMID 37238871, 2023). "Exosomal piRNA-17560 secreted by senescent neutrophils through the STAT3-dependent pathway plays a crucial role in inducing chemoresistance and promoting epithelial-mesenchymal transition in breast cancer cells." (PMID 37514090, 2023). "MafG accelerates cell proliferation and inhibits cell apoptosis in lung adenocarcinoma, while MafF promotes tumor invasion through heterodimerizing with Bach1 and activating the IL11/STAT3 pathway in breast cancer." (PMID 37491302, 2023). "Instead, the fact that PD-L1-induced activation of STAT3 and STAT1 requires, as a prerequisite, that PD-L1 will be N-linked glycosylated, provides novel perspectives to PD-L1-directed therapy in breast cancer patients." (PMID 37830552, 2023). "The NF-κB/GATA3/STAT3 signaling pathway provided a promising target for overcoming DOX resistance in breast cancer." (PMID 37781691, 2023). "STAT3 activation promotes integrin-mediated cell adhesion and intracellular signaling in breast cancer cells." (PMID 37836626, 2023). "ANXA2 has previously been demonstrated to activate STAT3 in macrophages and enhance the formation of breast cancer, pancreatic cancer and hepatoma." (PMID 36916296, 2023). "Compound C6 was also discovered to be a STAT3-specific inhibitor that had the strongest anti-proliferation activities against breast cancer cells with an IC50 value of 160 nM." (PMID 36829653, 2023). "Pentadecanoic acid is a JAK2/STAT3 signaling inhibitor in breast cancer cells and an anti-biofilm agent." (PMID 38005278, 2023). "To summarize, CAF-secreted IL-6 activates STAT3 signaling, which promotes breast cancer cell growth and radioresistance." (PMID 36635302, 2023).
breast cancer (continued). "In the study conducted by Rahmati and colleagues, the STAT3 ODN-decoy was used for breast cancer therapy." (PMID 38067351, 2023). "JAK2/STAT3 activation promotes breast cancer cell growth, survival, and metastasis via EMT induction and chemotherapy resistance." (PMID 36674719, 2023). "Blocking either hyaluronan synthesis or STAT3 activation reverses proliferation and doxorubicin resistance of breast cancer cells." (PMID 38045829, 2023). "The STAT3 ODN-decoy delivered with trastuzumab by CaP@HA reduced BT474R breast cancer cells’ resistance to trastuzumab." (PMID 38067351, 2023). "A-FABP, which is highly expressed in TAMs of mouse and human breast cancer cells, enhances IL-6/STAT3 signaling by regulating the NF-κB/miR-29b pathway, thereby promoting breast cancer growth and metastasis." (PMID 37781517, 2023). "Fascinatingly, CSF1 and EGF establish a feedback paracrine loop between CSCs and TAMs, where CSF1 recruited TAMs shed a higher amount of EGF leading to stimulation of STAT3/SOX2 pathway in breast cancer cells." (PMID 38035101, 2023). "The effect of the combinatory therapy based on trastuzumab (TRAZ) with the STAT3 ODN-decoy delivered by nanoparticles in breast cancer that overexpressed HER2 was investigated." (PMID 38067351, 2023). "STAT3/HIF-1α signaling pathway inhibition can attenuate the resistance of breast cancer cells to adriamycin." (PMID 37628777, 2023). "The RNA binding protein EIF4A3 is considered as an important regulator of post-transcriptional regulatory processes, and CCL2, as a powerful macrophage chemokine, was reported to be a target of STAT3 in breast cancer." (PMID 36797769, 2023). "Pyrimethamine suppresses STAT3 action in metastatic breast cancer cell lines ex-vivo by reducing tumor growth and invasion and by increasing Lamp1 production in tumour-infiltrating CD8+T lymphocytes." (PMID 37710280, 2023). "miR-214 expression correlates with IL-6 and STAT3 signatures in TCGA breast cancer and melanoma datasets." (PMID 36639824, 2023). "The silencing of STAT3 in 4T1 breast cancer cells by shRNA reduced c-MYC expression and TWIST protein level." (PMID 38067351, 2023). "CircRHOT1 was found to promote the proliferation and migration of breast cancer cells and inhibit apoptosis and ferroptosis through the miR-106a-5p/STAT3 axis." (PMID 37332354, 2023). "We used the MDA-MB-231 cell line which represents an aggressive and mortal subtype of breast cancer, in which STAT3 is overexpressed and constitutively activated." (PMID 37097001, 2023). "CXCL1 also acts on cancer-associated adipocytes, causing STAT3 activation in them, which leads to the production of LIF which in turn increases CXCL1 production in breast cancer cells." (PMID 37108425, 2023). "The abnormal expression of the signal transducer and activator of transcription 3 (STAT3) is observed in various malignancies, including breast cancer, pancreatic cancer, leukemia, and liver cancer." (PMID 37762016, 2023). "CypA/CD147 activation induces CSC features in breast cancer cells through the STAT3 and solute carrier family 34 member 2 (SLC34A2)/phosphatidylinositol-3-kinase (PI3K)/AKT/SRY-box transcription factor 2 (SOX2) signaling pathways." (PMID 36902161, 2023). "To investigate this possibility, we examined the effect of PRRG4 knockdown on STAT3 activation in breast cancer cells by immunoblotting with phospho-STAT3 (Tyr705) antibody (p-STAT3)." (PMID 38102641, 2023). "Specifically, we examined the effect of VaM on cell viability, proliferation, apoptosis induction, cell cycle progression, and regulation of the STAT3 signaling pathway in breast cancer cells." (PMID 37569363, 2023). "Behera and colleagues reported that osteopontin can bind αvβ3 integrin and induce JAK2/STAT3 activation in human breast cancer cells." (PMID 37614232, 2023). "The IL6/STAT3 pathway hijacked estrogen receptor alpha enhancers to promote cancer cell proliferation in breast cancer." (PMID 37298609, 2023).